ABCG2 (ATP binding cassette subfamily G member 2 (JR blood group))
Diseases named in the same sentence as ABCG2 in open-access papers (continued):
Sharing a sentence is not in itself a finding about the gene and the disease.
gout (continued). "In other words, when ABCG2 dysfunctional variation and A1CF variation exist at the same time, A1CF variation is significantly correlated with gout, but in the absence of ABCG2 variation, the correlation between A1CF variation and gout is no longer significant." (PMID 35922835, 2022). "The observation that adjustment for allopurinol intake was important in detecting genetic effects on gout in this study implies that allopurinol is a well working drug regardless of the observed SLC2A9 and ABCG2 genotype." (PMID 30181573, 2018). "Six genes (A1CF, ABCG2, SLC2A9, TRIM46, SLC17A1 and SLC17A4) exhibited effects on the development of gout from hyperuricemia in males (all P < 0.05), but none of them exhibited such effects in females (all P > 0.05)." (PMID 28252667, 2017).
hyperuricemia (188 papers, 2012 to 2026). An abnormally high level of uric acid. "Although premenopausal women generally had a lower prevalence of hyperuricemia than postmenopausal individuals, those with dysfunctional variants of ABCG2 tended to show a higher SUA increase and PAFs in premenopausal than in postmenopausal women." (PMID 42310200, 2026). "Silencing METTL3 in mice can improve the decline of the ABCG2 mRNA level caused by hyperuricemia; consistent results have been observed in vitro." (PMID 40100069, 2025). "The ABCG2 variants had higher PAF for the progression of hyperuricemia than other typical environment risk factors, i.e., overweight/obesity, heavy drinking, and aging." (PMID 41452549, 2025). "As a result, random-effect models were applied to these outcomes, confirming a causal relationship between ABCG2-mediated hyperuricemia and liver/bile duct cancer (ieu-b-4915), while excluding any such relationship with NAFLD." (PMID 40282409, 2025). "In the present study, we revealed that dysfunctional variants of ABCG2 carry a high individual and population risk of progression of hyperuricemia in both sexes." (PMID 41452549, 2025). "Early studies identified the nonsynonymous SNP rs2231142 in exon 5 of ABCG2 as being causally linked to hyperuricemia, reducing urate transport efficiency by 54% in oocytes." (PMID 40282409, 2025). "The ABCG2 rs2231142 variant (TT genotype) is associated with hyperuricemia (HUA), but the relationship between ABCG2 gene polymorphisms and coronary artery disease (CAD) risk is poorly elucidated." (PMID 39315221, 2024). "ABCG2 dysfunction is associated with reduced UA excretion, and patients with hyperuricemia show reduced ABCG2 expression." (PMID 39275356, 2024). "Genetic variants of ABCG2 in diverse populations have been linked to high risks of hyperuricemia and gout." (PMID 39433541, 2024). "The primary objective of the study was to determine the prevalence of self-reported nephrolithiasis in Taiwan and to identify the associations between the ABCG2 rs2231142 variant and incident nephrolithiasis with hyperuricemia." (PMID 36967798, 2023). "This retrospective case-control study using data from TWB revealed that besides higher age, males sex, smoking, overweight, comorbidities and hyperuricemia, the ABCG2 rs2231142 genotypes was independently associated with nephrolithiasis." (PMID 36967798, 2023). "Decreased extra-renal UA excretion, caused by ABCG2 dysfunction, is a common mechanism of hyperuricemia." (PMID 38042879, 2023). "The role of ABCG2 variants has been shown to be more important for the risk of hyperuricemia than environmental factors such as obesity and intense alcohol consumption." (PMID 37238926, 2023). "In other words, dysfunctional ABCG2 variants are the shared cause of hyperuricemia due to both renal overload and underexcretion of urate." (PMID 38137389, 2023). "In ESRD patients, a group with dysfunctional variants of the ABCG2 gene had reduced ABCG2-mediated intestinal urate excretion resulting in increased hyperuricemia." (PMID 36136564, 2022). "For example, the joint effect of alcohol consumption and carrying the risk allele of ABCG2 rs2231142 G > T was associated with a greater risk for developing hyperuricemia than the risk allele alone, especially among women." (PMID 36079846, 2022). "ABCG2 is a high-capacity UA transporter located on the apical membrane of enterocytes, the dysfunction of which raises hyperuricemia risk." (PMID 36245501, 2022). "Abcg2-knockout mice showed increased serum UA and renal UA excretion, and decreased intestinal UA excretion, indicating that a significance of decreased extra-renal UA excretion caused by ABCG2 dysfunction for hyperuricemia." (PMID 34502127, 2021).
hyperuricemia (continued). "ABCG2 in chromosome 4q22 encodes ATP-binding cassette subfamily G member 2 (ABCG2) that reduces the transportation activity, resulting in hyperuricaemia." (PMID 34545327, 2021). "Genetic variations in ABCG2 should be kept in mind during diagnostic procedures for pediatric-onset hyperuricemia." (PMID 33669292, 2021). "By generating a mouse model of the orthologous Q140K Abcg2 variant, they also found that male mice had significant hyperuricemia and metabolic alterations but only subtle alterations of renal urate excretion and ABCG2 abundance." (PMID 34144706, 2021). "Here, two commonly-studied missense polymorphisms (V12M; rs2231137 and Q141K; rs2231142) from the ABCG2 gene were selected on the basis of their potential involvement in the susceptibility of hyperuricemia for examining their association with psoriasis." (PMID 34680995, 2021). "Decreased extra-renal urate excretion caused by ABCG2 dysfunction is a common mechanism of hyperuricemia." (PMID 34946365, 2021). "It was also recently reported that the association of ABCG2 rs2231142 with hyperuricemia is modified by SLC2A9 polymorphism in an elderly Chinese population." (PMID 33531973, 2021). "ABCG2 variants have been shown to have stronger effects on the risk of hyperuricemia than major environmental risk factors such as aging, obesity, and heavy drinking." (PMID 34639563, 2021). "Specifically, GT/TT genotypes of ABCG2 rs2231142 were associated with a reduced risk of psoriasis and were more prone to develop hyperuricemia in psoriasis patients." (PMID 34680995, 2021). "ABCG2 genetic variants, common and rare, have been shown to have stronger effects on the risk of hyperuricemia than major environmental risk factors, such as obesity and heavy drinking." (PMID 34946365, 2021). "Future studies are warranted to elucidate the relationship between ABCG2 polymorphisms, dietary factors, and hyperuricemia." (PMID 34639563, 2021). "For instance, in a previous study on gene polymorphism analysis using the SNaPshot method, Han and Uyghur Chinese patients with hyperuricemia and Phlegm block were shown to harbor the rs2231137 allele C of the ABCG2 gene." (PMID 33671865, 2021). "Recent studies suggest that ABCG2 dysfunction causes a decrease in the uric acid excretion, especially in the intestine, resulting in hyperuricemia." (PMID 31254042, 2020). "Other ABCG2 SNPs were shown to be of functional value related to uric acid handling/transport, and were associated with early onset hyperuricemia and gout in Japanese population (rs2728125, rs223114)." (PMID 32715435, 2020). "ABCG2 overexpression has been linked to poor prognosis in several different haematological malignancies, and altered function of ABCG2 due to inherited polymorphisms is a major risk factor for hyperuricaemia." (PMID 32057756, 2020). "Intriguingly, we found homozygous Trp258* mutations in SLC22A12 gene causing RHUC1 while concurrent mutations reported to be associated with hyperuricemia were also discovered including ABCG2 (Gln141Lys) and SLC17A1 (Thr269Ile)." (PMID 32375679, 2020). "The ABCG2 rs2231142 single nucleotide polymorphism (SNP) is one of the most significant genetic variants associated with hyperuricemia (HUA) in Asian populations." (PMID 32183743, 2020). "We explore mechanisms by generating a mouse model of the orthologous Q140K Abcg2 variant and find male mice have significant hyperuricemia and metabolic alterations, but only subtle alterations of renal urate excretion and ABCG2 abundance." (PMID 32488095, 2020). "The broad substrate specificity of ABCG2 also underpins physiological roles in extra-renal urate transport, and disruption of ABCG2 urate transport function due to single nucleotide polymorphisms is a powerful predictor of serum hyperuricemia." (PMID 31979415, 2020).
hyperuricemia (continued). "We also reported that hyperuricemia causes decreased expression of breast cancer resistance protein (BCRP, ABCG2) transporter in the plasma membrane of vascular endothelial cells, resulting in a nonlinear increase of cellular uric acid accumulation." (PMID 30951542, 2019). "In conclusion, this study confirms the association between the SLC2A9 and ABCG2 genes and hyperuricemia." (PMID 31207883, 2019). "The ABCG2 population-attributable percent risk for hyperuricemia has been reported to be 29.2%, which is much higher than those with more typical environmental risks, i.e., BMI ≥ 25.0 (18.7%), heavy drinking (15.4%), and age (≥ 60 years old, 5.74%)." (PMID 30894219, 2019). "ABCG2 dysfunction was also reported to be a strong independent risk factor for pediatric-onset hyperuricemia." (PMID 31652657, 2019). "In the Taiwanese population, the ABCG2 rs2231142-A allele had a higher frequency of hyperuricemia in males or obese individuals." (PMID 31491937, 2019). "Among them, common abnormalities of ABCG2 exporter has been shown to be a major cause of hyperuricemia and gout." (PMID 31227765, 2019). "Genetic variation in human ABCG2, an ATP-driven efflux pump on the apical membrane proximal tubule epithelial cells, has emerged as a major factor in human hyperuricemia and gout risk." (PMID 29904633, 2018). "Previously, some studies demonstrated that ABCG2 contributed to hyperuricemia, which was caused by renal urate overload and intestinal urate under-excretion." (PMID 29453348, 2018). "Although researchers are becoming increasingly aware that decreased extra-renal urate excretion caused by ABCG2 dysfunction is a common mechanism of hyperuricemia, the effect of soluble uric acid on urate excretion is not completely understood." (PMID 29415757, 2018). "In conclusion, chicory has the uricosuric effect in fructose-induced hyperuricemia rats, which was associated to accelerating intestinal excretion of uric acid by up-regulating the mRNA and protein expressions of ABCG2 in the intestine." (PMID 28630638, 2017). "And actually, uric acid was absorbable, because hyperuricemia model was able to be established by oral intake of uric acid both in mice and quails, and some transporter associated like ABCG2 was found in intestinal tract." (PMID 29267361, 2017). "More recently, Matsuo et.al also reported that the ABCG2 variant responsible for hyperuricemia increased FEUA." (PMID 27105641, 2016). "Genetically, decreased ABCG2 function is one of the major risk factors of hyperuricemia, since ABCG2 contributes to both intestinal and urinary excretion of urate from the human body into the feces and urine, respectively." (PMID 28082903, 2016). "The ATP-binding cassette transporter ABCG2 has been established as a high capacity urate transporter, is expressed in renal proximal tubules, liver and intestines, and the hyperuricemia causal Q141K mutation has been shown to reduce urate transport rates." (PMID 25811787, 2015). "Our results confirm that this alteration in the ABCG2 gene is a common cause of hyperuricemia due to decreased renal urate excretion." (PMID 24827988, 2014). "Similar results were obtained from all participants when hyperuricemia was defined as SUA of > 6.0 mg/dl in females: ABCG2 variants [PAF = 30.3%, 95% CI, 25.1–35.4, RR = 1.81 (95% CI, 1.63–2.02; P = 1.86 × 10–28)] had higher impacts than other typical environmental factors." (PMID 41452549, 2025). "•ABCG2 rs2231142 TT genotype is associated with hyperuricemia." (PMID 39315221, 2024). "Urate synthesis inhibitors in general are favoured in ROL type hyperuricemia as well, however ABCG2 dysfunction might be linked with poor therapeutic response to the first drug of choice allopurinol." (PMID 35939175, 2023). "Thus, the screening of ABCG2 rs2231142 variants is as important as the evaluation of systemic comorbidities and lifestyle factors for patients with nephrolithiasis and hyperuricemia." (PMID 36967798, 2023).
hyperuricemia (continued). "ABCG2 is a high-capacity UA exporter, the dysfunction of which raises hyperuricemia risk." (PMID 36831103, 2023). "However, our result provides robust evidence that ABCG2 rs2231142 genetic variations are associated with both hyperuricemia and incident nephrolithiasis." (PMID 36967798, 2023). "Unlike controls, in patients, there is a high probability of the presence of inflammation caused by hyperuricemia or its comorbidities, which may favor the expression of ABCG2." (PMID 35505381, 2022). "Q141K and Q126K are the two variants of ABCG2 that cause hyperuricemia." (PMID 35281005, 2022). "While the role of ABCG2 in multidrug resistance is widely recognized, the dysfunction of ABCG2 gene can be induced by other factors, such as genetic polymorphisms, which have been proven in several diseases, such as hyperuricemia and hypertension in humans." (PMID 36555598, 2022). "Abcg2/Bcrp1 knockout mice showed increased plasma levels of urate, and multiple GWAS studies demonstrated associations between human allelic variants with impaired urate transport in vitro and hyperuricemia." (PMID 34204277, 2021). "Genotype and allele frequencies of ABCG2 rs2231142 and risk of hyperuricemia in the participants." (PMID 34531894, 2021). "Additionally, there is extensive evidence that variants in ABCG2 cause hyperuricemia in young people." (PMID 34063419, 2021). "First of all, this study was a population-based study and explored the effects of interaction between ABCG2 rs2231142 risk allele and BMI on hyperuricemia in a population with a large sample size, which provided enough power for multiple logistic regression analysis and interaction analysis." (PMID 34531894, 2021). "ABCG2 dysfunction caused by common variants will significantly increase the risk of hyperuricaemia, and the reduction of extra renal urate excretion through dysfunctional ABCG2 is a common mechanism of hyperuricaemia." (PMID 34335246, 2021). "This type of genetic information will also allow a personalized approach regarding the best urate-lowering treatment (i.e., uric acid production inhibitors or uricosuric agents) for patients with dysfunctional ABCG2 variants, as well as the best time to initiate pharmacotherapy for hyperuricemia." (PMID 33669292, 2021). "Furthermore, Q140K+/+ knock-in mice have hyperuricemia, driven by an almost complete loss of ABCG2-mediated urate excretion in the small intestine." (PMID 32488095, 2020). "Therefore, the loss of intestinal urate secretion appears to drive the hyperuricemia in the Q140K+/+ ABCG2 mice and potentially in the 141K variant carriers in our clinical cohort." (PMID 32488095, 2020). "Since ABCG2 is the main urate transporter in both the kidney and intestine, previous studies reported that dysfunctional ABCG2 gene polymorphisms are associated with hyperuricemia by decreasing urate excretion." (PMID 32180207, 2020). "For example, ABCG2 dysfunctional variants have a strong impact on the progression of hyperuricemia." (PMID 32090094, 2020). "The ABCG2 Q141K (rs2231142) and rs10011796 variants associate with hyperuricaemia (HU)." (PMID 32164793, 2020). "Defects on the ABCG2 gene were shown to be associated with hyperuricemia and gout." (PMID 31891613, 2019). "Additionally, under the additive model, we observed statistically significant associations between hyperuricemia and the ABCG2 SNPs and SLC2A9 genes." (PMID 31207883, 2019). "Importantly, we recently reported that decreased extra-renal urate excretion caused by ABCG2 dysfunction is a common mechanism of hyperuricemia." (PMID 31003562, 2019). "However, in the present study we identified two previously reported loci (SLC2A9 and ABCG2) associated with the serum levels of UA and hyperuricemia." (PMID 31207883, 2019). "In addition, ABCG2 variants have been reported to show stronger effects on hyperuricemia than main environmental risk factors such as obesity, age, and alcohol drinking." (PMID 31227765, 2019).